USP7 (ubiquitin specific peptidase 7)
Diseases named in the same sentence as USP7 in open-access papers (continued):
Sharing a sentence is not in itself a finding about the gene and the disease.
cancer (continued). "As a result, USP7 has emerged as a promising target for cancer therapy." (PMID 37946202, 2023). "Furthermore, data from The Cancer Genome Atlas (TCGA) also indicate a positive correlation between USP7 and SAMHD1 expressions in various cancer types." (PMID 37081042, 2023). "In addition, the targeted inhibition of USP7 significantly increases PD-L1 protein levels in both cancer cells and the tumor microenvironment." (PMID 37415977, 2023). "Second, we also examined the impact of USP7 inhibition through upregulation of USP22 on H2Bub1, which is a well-known and key target of USP22 in cells and is associated with more malignant phenotype and poor prognosis of various cancers." (PMID 37946202, 2023). "USP7 is highly expressed in a variety of cancers and affects cancer development." (PMID 38276639, 2023). "Deletion of USP7 in cancer cell lines and organoids inhibits WNT activation by restoring β-catenin ubiquitination specifically in APC-mutated, but not wild-type (WT), cells, suggesting that USP7 may represent a tumor-specific drug target." (PMID 36669491, 2023). "Consequently, induction of ER stress by USP7 inhibitors induces oxidative stress and cancer cell apoptosis." (PMID 37874827, 2023). "Previous studies have documented that USP7 may play contradictory roles, pro-tumorigenic or anti-neoplastic, across diverse cancer contexts." (PMID 35931679, 2022). "However, the efficacy of USP7 inhibitors has yet to be shown in a cancer patient population carefully selected with the use of genetic and immunological markers that reflect the complex biological role of USP7." (PMID 36428632, 2022). "Thus, the application of USP7 inhibitors alone and in combination with cancer immunotherapeutics is highly promising." (PMID 36428632, 2022). "USP7 has attracted much attention because of its role in various cancers." (PMID 35414773, 2022). "Upregulation of USP7 is frequently observed in various types of cancer, and the apparent contribution of this upregulation to carcinogenesis has led to speculation that USP7 could be an effective target in anticancer therapies." (PMID 36291159, 2022). "This mini review systematically summarizes the role of USP7 as a drug target for cancer therapeutics, as well as the scaffolds, activities, and binding modes of some of the most representative small molecule USP7 inhibitors reported in the scientific literature." (PMID 36186590, 2022). "Collectively, this information suggests a regulatory role for USP7 in neurodegeneration and cancer." (PMID 35159365, 2022). "Ubiquitin-specific protease 7 (USP7) is highly expressed in a variety of malignant tumors." (PMID 35955807, 2022). "USP7, one of the most important DUBs, stabilizes many proteins crucial to tumor cell viability, and therefore it is gaining attention as a potential target for cancer treatment." (PMID 36428632, 2022). "Parthenolide, found in feverfew, inhibits the activity of Wnt signaling by directly acting on ubiquitin-specific peptidase 7 and destabilizing β-catenin, which indicates that parthenolide is a target anti-cancer agent for aberrant ubiquitin-specific peptidase 7/Wnt signaling." (PMID 36158694, 2022). "By examining the Cancer Dependency Map, we identified genes whose survival dependency correlated with that of USP7 across cancer cell lines, with the rationale that survival codependency implies that such genes may function within the same complex or pathway." (PMID 35775490, 2022).
cancer (continued). "Normal USP7 functions are necessary for the maintenance of cellular homeostasis, while its aberrant expression may lead to the development of cancer." (PMID 36428632, 2022). "USP7 inhibitors are potential therapeutic targets for inducing cancer cell apoptosis." (PMID 35571490, 2022). "Hence, clinical doctors should pay more attention to cartilage if the USP7 inhibitor is used for cancers patients with OA." (PMID 35432716, 2022). "Since USP7 is a deubiquitinating enzyme that interacts with Mdm2 and prevents its ubiquitination and degradation, targeting USP7 can be an alternative approach for cancer treatment." (PMID 36180910, 2022). "It is well known that USP7 mainly binds with specific target proteins, brings in an E3 Ub ligase or modulates the activity of the deubiquitinating enzyme which influence various cellular pathways related to cancer." (PMID 35864588, 2022). "Therefore, the development of potent and selective small molecule inhibitors of USP7 has the potential to be a promising treatment for cancers and other disorders and has become a highly sought-after goal." (PMID 36186590, 2022). "This suggests USP7 as a promising prognostic and druggable target for cancer therapy." (PMID 36186590, 2022). "Recent studies show that USP7, which is involved in tumor-genesis and process, could be used for novel drug target in cancer therapy." (PMID 34812471, 2021). "Our data indicate that USP7 could regulate PRC2 complex by two ways to promote tumorigenesis, supporting the pursuit of USP7 as a potential target for cancer therapy." (PMID 33849069, 2021). "USP7/HAUSP has been deeply studied from the structure/function standpoint and its molecular signaling pathway is well established and considered a potential therapeutic target for cancer." (PMID 33498168, 2021). "Besides, targeting USP7 inhibits cell apoptosis in response to chemo-/radiotherapy, indicating the promising role of USP7 inhibitors in reducing adverse reactions in cancer treatment." (PMID 34869041, 2021). "The relationship between USP7 and cancer cell invasion is known." (PMID 34753486, 2021). "Therefore, in order to ensure the availability and effectiveness of USP7 inhibitors in cancer therapy, evaluation of drug safety is very necessary, which requires more data from in vivo experiments." (PMID 34869041, 2021). "Studies have demonstrated the duality of USP7 functions in cancer progression." (PMID 34869041, 2021). "This review describes the functions of USP7 and the regulatory mechanisms of its expression and activity, aiming to emphasize the necessity of research on USP7, and provide a better understanding of USP7-related biological processes and cancer." (PMID 34869041, 2021). "Furthermore, it was shown that UbV.7.2 inhibited activity of USP7 in vitro and in cells; and conferred chemotherapeutic synergistic effect in combination with cisplatin for increasing cancer cell death and improving cancer treatment." (PMID 33466790, 2021).
cancer (continued). "Excitingly, the combination of USP7 inhibitors and several current major cancer treatments has been shown to possess promising therapeutic prospects, mainly including chemotherapy, radiotherapy, and immunotherapy (such as PD-L1 treatment), which will be one of the study directions in the future." (PMID 34869041, 2021). "Thus, discovery of potent small-molecule USP7 inhibitors is a long sought-after avenue for cancer therapeutics." (PMID 34203106, 2021). "Recently, many studies have shown that dysregulated cell processes mediated by USP7 may contribute to numerous diseases, such as cancers." (PMID 34869041, 2021). "Specific mechanisms that could explain how USP7 interacts with its substrates in apoptosis are needed to explore the different roles of USP7 in various cancers." (PMID 34869041, 2021). "Aside from monotherapy-type approaches, several publications in the past decade have indicated USP7 inhibitors might also be effective in cancer treatment, in combination with other chemotherapeutic agents." (PMID 32850836, 2020). "Ubiquitin-specific protease 7 (USP7), also named as herpesvirus-associated ubiquitin-specific protease (HAUSP) is one of the most investigated DUBs and has been associated with the initiation and progression of various cancers." (PMID 32300595, 2020). "For instance, USP7 acts as a positive regulator of Hh signaling by deubiquitinating and stabilizing Ci and Gli proteins, indicating that Gli is a significant potential therapeutic target for Hh-related cancers." (PMID 33158118, 2020). "However, compared to extensive studies regarding USP7 in several other cancers, the function of USP7 in HCC remains to be fully addressed." (PMID 32002017, 2020). "With an increasing interest and effort in the development of USP7 inhibitors for cancer therapy, more specific and potent USP7 inhibitors may become available in the near future." (PMID 32064756, 2020). "Moreover, comparison of the sensitivity profile of XL177A across over 400 cancer cell lines with sensitivity profiles generated in those same cell lines with KD / KO of over 18,000 genes identified USP7 KO as exhibiting the most similar profile." (PMID 32210275, 2020). "Furthermore, low USP7 expression levels were found to be an indicator of poor patient prognosis, supporting a role for USP7 in suppressing cancer progression by maintaining genome stability." (PMID 32850836, 2020). "Identification of USP7 as a promising gene editing candidate might open up the possibility of new molecular drug research in targeting the ubiquitination pathway in cancer." (PMID 32922122, 2020).
cancer (continued). "USP7 is overexpressed in human cancers and contributes to cancer initiation and progression." (PMID 32300595, 2020). "In addition, we measured the activity of caspase 3 in USP7-depleted cancer cells using a caspase 3-specific fluorogenic substrate." (PMID 33207738, 2020). "Epidemiological and clinical evidence connecting USP7 and cancer." (PMID 32300595, 2020). "The frequent up-regulation of USP7 in many cancer types and the apparent contributions of this upregulation to carcinogenesis, has led to speculation that USP7 could be an effective target in anti-cancer therapies." (PMID 32850836, 2020). "Therefore, based on the current literature, pharmacological inhibitors of USP7 are promising anticancer agents in various carcinomas, depending on the cellular context." (PMID 33207738, 2020). "These experimental results suggest that targeting mitotic oncogenic factors, such as PLK1 and USP7, may be effective for treating carcinomas that have resistance to mitotic catastrophe." (PMID 33207738, 2020). "First, USP7 is highly expressed in several carcinoma patients and its expression peaks in mitosis." (PMID 33207738, 2020). "The data further validated that USP7 may be a reliable biomarker of taxane resistance, in addition to a biomarker of cancer malignancy." (PMID 31730000, 2019). "However, no DUB inhibitor has stepped up to clinical trials, though the USP7 inhibitor P5091 showed significant anti-cancer effects in pre-clinical tests." (PMID 31730000, 2019). "USP7 is a promising target not only for its roles in cellular pathways including regulators of viral proteins, immune response, oncogenes, and DNA damage but also because of its aberrant expression in various cancers." (PMID 31114498, 2019). "Besides, USP7 inhibitors can be combined with genotoxic agents as a novel therapeutic strategy for the treatment of cancer." (PMID 31114498, 2019). "In addition to USP22, USP7 and 12 have also been reported to be more highly expressed in PCa compared to non-cancer tissue by IHC20,22." (PMID 30177856, 2018). "Like USP7, USP11 appears to have multiple cancer-associated roles, that could either promote or suppress oncogenesis and therefore a better understanding of the USP7-USP11 interaction is warranted." (PMID 30367141, 2018). "USP7 expression closely correlates with cancer stage, tumor size and prognosis, which indicates that USP7 may be a prognostic marker in certain cancers." (PMID 30319415, 2018). "USP7 has been found to be a drug target in several cancer types." (PMID 30370059, 2018). "However, to better understand the contributions of USP7 to cancer, a more thorough understanding of its interactions in cancer cells is needed." (PMID 30367141, 2018). "Our data suggest that USP7 inhibitors can be used for treatment of CID-deleted APC mutated CRCs, as well as for potential preventive therapy for FAP patients carrying germline APC mutations, by delaying cancer onset." (PMID 29045831, 2017). "DUBs are critical key players in diverse processes such as (i) spermatogenesis (e.g. USP2, USP8, USP9y, USP14, USP26, Uchl-1, Uchl-3 and CYLD), (ii) cancer biology (e.g. USP7, USP10 and USP11), and (iii) stemness and differentiation (e.g. USP7, USP9x, USP22, USP44 and Psmd14)." (PMID 28659380, 2017).
cancer (continued). "Moreover, altered levels of CCDC6 protein in cancer cells seem to depend on the altered turnover of CCDC6 protein regulated by the de-ubiquitinase USP7." (PMID 28415632, 2017). "Because CDDO-Me and its related synthetic triterpenoids have entered clinical trials as promising preventive and therapeutic agents for cancer and chronic inflammatory diseases, development of novel USP7-selective compounds based on the CDDO-Me scaffold warrant further investigation." (PMID 27780924, 2016). "Targeting USP7 is becoming an attractive strategy for cancer therapy." (PMID 27780924, 2016). "USP7 is a cellular protein that binds and stabilizes many proteins involved in multiple pathways that regulate oncogenesis and as such is recognized as a potential target for cancer therapy." (PMID 26046769, 2015). "During cancer development, Usp7 plays an oncogenic role as it promotes cellular survival." (PMID 25962961, 2015). "Some DUB inhibitors, such as inhibitors of USP7, are being investigated as anti-cancer drugs." (PMID 22335355, 2012). "Hence, the relationship between USP7 and cancer progression is remarkable." (PMID 40061891, 2025). "Importantly, increased USP22 expression leads to significant activation of downstream signal pathways including H2Bub1 and c-Myc, which may potentially enhance cancer malignancy and counteract the anticancer efficacy of USP7 inhibition." (PMID 37946202, 2023). "Ubiquitin-specific proteases (USPs) constitute the largest DUB subfamily, of which USP7 is a key deubiquitinating enzyme stabilizing multiple substrates through deubiquitination, thereby regulating a variety of cellular processes including immune response, virus replication, and cancer." (PMID 37081042, 2023). "Therefore, it may be highly effective to boost cancer immunotherapy by the co-treatment of USP7 inhibition plus MDM2 blockage and anti-PD-1 therapy." (PMID 37658402, 2023). "Indeed, USP7 has emerged as a target for drugs that target specific cancers." (PMID 37014752, 2023). "Also, deleting USP7 made cancer cells more vulnerable to T cell death, both in vitro and in vivo." (PMID 36624687, 2023). "Although the influence of these compounds on various pathways in the development of cancer malignancies has been investigated thoroughly, their ability to modulate anti-tumor immune response was evaluated only for a small number of previously reported USP7 inhibitors." (PMID 36428632, 2022). "To investigate whether USP7 knockdown could also sensitize cells from other cancer entities to PI3K pathway inhibition, we utilized the human CRC (Caco2-TA, LoVo-TA) and HCC (HEP-3B; HuH7-TA) cell lines harboring the constructs with strongest USP7 knockdown after 4 and 8 days of Dox treatment." (PMID 35673573, 2022). "Therefore, our results reveal that RNF6 is a RING E3 ligase that undergoes auto-ubiquitination, which could be abolished by USP7 and induced by anti-cancer drugs." (PMID 35926709, 2022).